SNORA49 (small nucleolar RNA, H/ACA box 49)
Synonyms: ACA49
Gene: Small nucleolar RNA gene on chromosome 12 (132,031,224 to 132,031,359, forward strand). Ensembl gene ENSG00000208892.
Gene Ontology:
Biological process: RNA processing
Cellular component: nucleolus
Homologues: Orthologues: chimpanzee SNORA49 (100% identical), macaque SNORA49 (97% identical), mouse Gm26079 (86% identical), rat Snora49 (86% identical), guinea pig SNORA49 (83% identical), pig SNORA49 (80% identical).